IL10 (interleukin 10)
Diseases named in the same sentence as IL10 in open-access papers (continued):
Sharing a sentence is not in itself a finding about the gene and the disease.
COVID-19 (continued). "Through no specific mechanism for HLA-G up-regulation has been outlined during the SARS-CoV-2 infection, COVID-19 patients peripheral circulation highly increased cytokines such as IL-10, GM-CSF and IDO could be factors involved in the HLA-G expression modification." (PMID 34938296, 2021). "Furthermore, a positive correlation was found between the cMono Phenograph clusters specific to severe COVID-19 (clusters 2, 9, 10, and 18) and the soluble immunosuppressive factors IL-10, TGF-β, and VEGFA, as well as with AREG, the latter known to be involved in tolerance and tissue repair." (PMID 33479167, 2021). "In patients with COVID-19 hospitalized in intensive care units, elevated serum levels of IL-1β, IL-7, IL10, IL-17, IL-2, IL-9, Th17, IFN-γ, GM-CSF, G-CSF, IL-8, TNF-α, MIP1B, MCP1, MIP1A, and IP10 were observed, suggesting that the relation between periodontitis and COVID-19 may be established." (PMID 34068221, 2021). "IL-6, IL-8, IL-10, and Ts cell might be independent predictors for the poor outcome of COVID-19." (PMID 33542929, 2021). "Interestingly, while many of these cytokines and chemokines were also elevated in SARS and MERS patients, several studies have reported an increase in Th2-related anti-inflammatory cytokines IL-4 and IL-10 in COVID-19 patients, ascribing a seemingly unique cytokine profile to COVID-19." (PMID 34452323, 2021). "Additionally, CD8+ T cells had a predominant monofunctional response with high IL-10 production in mild COVID-19 but a bifunctional response dominated by CD107a+granzymeB+ and CD107a+perforin+ CD8+ T cells in asymptomatic infection suggesting an important role of spike-specific-CD8+ T cells." (PMID 34669281, 2021). "Notably, chronic upregulation of IL-10 has already been shown to contribute to the progression of inflammatory diseases, as it might occur in later/severe stages of COVID-19." (PMID 33673459, 2021). "To further validate the findings, as disease severity progresses in patients with COVID-19, we detected a concomitant rise in serum cytokine levels associating immune cell communication, such as IL6, IL10, IGF1, and GALECTIN-1, may play roles on reduction and exhaustion of T cell populations." (PMID 34238338, 2021). "Thus, therapies targeting IL-6 and IL-10 could be investigated as a means for improving NK cell antiviral immunity, especially in severe cases of COVID-19." (PMID 35062250, 2021). "Moreover, inhalation of welding fumes (mainly containing zinc) both increases pneumonia and cardiovascular risk and induces fever, fatigue, muscle ache, cough, dyspnoea, and a cytokine storm including IL-6 and IL-10, thus resembling the symptoms observed in COVID-19 patients." (PMID 33673459, 2021). "In addition, the IL-6:IL-10 and TNF-α:IL-10 ratios were significantly lower in COVID-19 patients as compared to non-COVID-19 patients (p = 0.0042 and p = 0.0001, respectively), driven by lower IL-6 and TNF-α levels in COVID-19 patients with similar levels of IL-10 between groups." (PMID 33272291, 2020). "However, IL-10-mediated immune suppression could drive the onset of secondary infectious complications and morbi-mortality, especially since 59% of COVID-19 patients presented at least 1 VAP event." (PMID 33272291, 2020). "We can speculate that the production of IL-10 in vivo derives mainly from cell types other than T lymphocytes, or T lymphocytes become exhausted regarding IL-10 production or there is an impairment of a specific T cell subset in COVID-19 patients." (PMID 33634100, 2020). "Additionally, studies have documented high levels of some TH2 immune cells in COVID-19 patients (e.g. IL-4 and IL-10); although it has been suggested that these represent normal immune responses to SARS-CoV-2 tissue damage geared toward regulating inflammation and repairing tissue." (PMID 33235797, 2020). "High levels of interleukin-10 were also observed in our study, whether COVID-19-related or not, and were independently associated with the duration of MV." (PMID 33272291, 2020).
COVID-19 (continued). "The present data indicate that DPSC administration might be effective in patients with COVID-19-induced hyper-inflammation, due to the inhibition in the production of several cytokines by activated T lymphocytes, namely, IFNγ, TNFα, IL-2, IL-9, IL-10, IL-17A, IL-18, IL-21, and IL-27." (PMID 33634100, 2020). "Moreover, elevated IL-6 and IL-10 levels in COVID-19 cases can suppress NK cell activity." (PMID 32973527, 2020). "Interestingly, the numbers of total T cells, CD4+ T and CD8+ T cells are negatively correlated to levels of TNF-α, IL-6, and IL-10, respectively, suggesting these cytokines may be involved in the decrease of T cells detected in COVID-19." (PMID 32425950, 2020). "Finally, alterations in the production of IL-10 and IL-18 by T lymphocytes might be involved in COVID-19 pathogenesis." (PMID 33634100, 2020). "Hence, elevation of IL-10 and TGF-β levels might curtail the hyperinflammatory storm observed in COVID-19 patients associated with poor prognosis." (PMID 32758273, 2020). "In addition, this study indicated that although COVID-19 patients with severe illness in the first days from symptoms onset exhibited augment of IL-6 and IL-10, at late days from symptoms onset, they showed increased levels of IFN-α and IFN- λ, IL-17, IL-22, eotaxin, IL-13, and a reduction of IL-6." (PMID 33584667, 2020). "We demonstrate here that COVID-19 patients have very high levels of serum IL-10 following SARS-CoV-2 infection, while also displaying high levels of the PD-1 and Tim-3 exhaustion markers on their T cells, suggesting that IL-10 might be mechanistically responsible." (PMID 32425950, 2020). "We proposed that the possible effects of hUCMSCs might be anti-inflammation and tissue repair to COVID-19 patients, and it was also reported that MSCs could down regulate proinflammatory cytokines and chemokines and increase IL-10 and VEGF which could promote the lung repair." (PMID 32756149, 2020). "In serum samples, soluble TLR-2 and TLR-4, IL-1β, IL-4, IL-6, Il-10, IFN-α, and TNF-α levels were significantly decreased in patients with coronavirus disease-19 (COVID-19) as compared with other viruses (p < 0.05 in each)." (PMID 41766850, 2026). "Notably, cytokines such as TNF-α, IL-1β, IL-6, IFN-γ, and IL-10 not only amplify the production of additional cytokines—including themselves—but also play critical roles in regulating immune cell differentiation and function, thereby exacerbating immune dysregulation in severe COVID-19." (PMID 41596316, 2026). "Significantly higher expression of IFN-γ (p = 0.0153), IL-6 (p < 0.0001), IL-10 (p < 0.0001), IL-17A (p = 0.0310), and TNF-α (p = 0.0034) was observed in COVID-19 patients compared to uninfected participants." (PMID 42023234, 2026). "The analysis of cord blood samples at Early and Intermediate convalescent COVID-19 showed increased levels of CCL11, CCL3, CCL4, CCL2, IL-1β, IFN-γ, IL1-Ra, G-CSF, and IL-7 and a decrease of IL-10 and IL-2 as compared with HC." (PMID 40821818, 2025). "Our findings highlight the critical role of various laboratory biomarkers, including hematological indices such as Neutrophil count and NLR as well as inflammation biomarkers like CRP and serum IL-10, in monitoring the severity of ARDS in COVID-19 patients." (PMID 40761632, 2025). "In summary, our study found that SP-D and IL-10 exhibited certain predictive abilities for the development of ARDS and pulmonary fibrosis in patients with COVID-19." (PMID 40160824, 2025). "When comparing the frequency of patients with elevated levels of IL-10, IL-6, and TNF-α and their combinations or overlaps, we found a significant difference (p < 0.001) between the non-, moderate, severe, and critical COVID-19 groups." (PMID 40508859, 2025). "In COVID-19, severe outcomes have increased levels of pro-inflammatory and anti-inflammatory cytokines and chemokines, such as IL-6, TNF-α, IL-10, CCL2, CCL3, CXCL8, and CXCL10, among others." (PMID 40881695, 2025).
COVID-19 (continued). "Recent investigations in sepsis, ARDS, and COVID-19 have consistently shown that integrating IL-6 with cytokines, such as IL-8, TNF-α, and IL-10, enhances discrimination for mortality, organ failure, and disease severity." (PMID 41155261, 2025). "Our results also showed an increase in circulating IL-6, IL-10, and TNF-α levels in critical COVID-19 patients after 10 days of hospitalization, highlighting the importance of quantifying these cytokines longitudinally in COVID-19 patients." (PMID 40508859, 2025). "At low exposure levels, COVID-19-positive individuals maintained consistent production of TNF, IL-2, IL-10, and IL-6, with multiple IFN-γ peaks." (PMID 40406109, 2025). "SP-D and IL-10 exhibited certain predictive abilities for the development of ARDS and pulmonary fibrosis in patients with COVID-19." (PMID 40160824, 2025). "During severe COVID-19-related ARDS (acute respiratory distress syndrome), specific proinflammatory cytokines such as IL-6, IL-8, and IL-10 appear at higher levels." (PMID 40497938, 2025). "Patients with COVID-19, severe pneumonia, or ARDS had elevated levels of interleukin (IL)-6, IL-10, and granulocyte colony-stimulating factor (G-CSF)." (PMID 40725841, 2025). "Notably, IL-2R, IL-6, IL-7, IL-8, and IL-10 showed lower correlations with the metabolites for the worst outcomes, indicating that these cytokines might have different regulatory mechanisms during severe COVID-19." (PMID 41002992, 2025). "We and others demonstrated that several cytokines and chemokines including IL‐2, IL‐6, IL‐7, IL‐10, IL-15, IL-17, IP‐10, MCP‐1, TNF‐α, GCSF were related to disease severity and mortality in COVID-19." (PMID 40315230, 2025). "Our results identify IL-6 and TNF as critical therapeutic targets against COVID-19 in SLE patients, whereas IL-10 relates closely to severe outcomes." (PMID 40643149, 2025). "There is a substantial amount of data on cytokine storm syndrome in COVID-19 patients, particularly high circulating levels of IL-6, IL-10, IL-2R, IL-8, and TNF-α in COVID-19 patients with high mortality rates." (PMID 40508859, 2025). "Supervised machine learning algorithm (RF) was used to predict the COVID-19 severity and chronicity based on immune subset profiling and a 14-plex cytokine panel (TNF-a, IL-4, IL-13, IL-2, GM-CSF, sCD40L, CCL5, CCL3, IL-6, IL-10, IFN-g, VEGF, IL-8, and CCL4." (PMID 40657638, 2025). "In line with other findings, IL-1ra, IL-10, and IFN-γ were significantly elevated in patients with severe COVID-19." (PMID 40087795, 2025). "Fifteen T-cell subsets were identified in COVID-19 convalescent LTRs, and it was shown that only terminal effector CD8+ - 3 decreased in the nAb+ group, while elevated IL-10 expression levels were found in the nAb- group." (PMID 40242765, 2025). "A drastic cytokine storm, characterized by considerably increased IL-6, IL-8, IL-10, TNF-α, and IFN levels in COVID-19 patients, leads to systemic inflammatory immune responses." (PMID 40872762, 2025). "Kynurenine was strongly correlated with IL-10, IL-8, IL-7, IL-6, IL-2R, IL-12, and IFN-α levels in patients with COVID-19." (PMID 41002992, 2025). "At very high exposure level, COVID-19-positive individuals demonstrated a continuous increase in IFN-γ, IL-2, IL-6, and IL-17A, while TNF peaked early and IL-10 showed minimal expression." (PMID 40406109, 2025). "IL-10 exhibited the strongest negative association with PaO2/FiO2 (Standardized B = -0.487, P < 0.001), indicating that increased levels of this anti-inflammatory cytokine may contribute to the deterioration of oxygenation in COVID-19-related ARDS." (PMID 40761632, 2025). "The present study aimed to characterize IL-6/IL-10 trajectories and determine the predictive efficacy of the DBS for clinical outcomes in hospitalized COVID-19 patients, benchmarking it against WHO-CPS and IL-6 as a standalone biomarker." (PMID 41322840, 2025).
COVID-19 (continued). "Another study has expanded results with elevated levels of plasma cytokines (IL-2, IL-7, IL-10, G-CSF, IP-10, MCP-1, MIP-1α, and TNF-α) in COVID-19 patients requiring Intensive Care Unit (ICU) admission compared to non-ICU patients." (PMID 38568894, 2024). "The elevated serum levels of IL-6, IL-10, and TNF-α have been correlated with disease severity and mortality in COVID-19 patients." (PMID 38932387, 2024). "In particular, elevated levels of IL-6, IL-7, IL-10, IL-17, IL-23, TNFα, IFN-γ, IFNα or IL-1β have been found in severe COVID-19 cases and have already profoundly been analysed in recent Meta-Analysis." (PMID 38298642, 2024). "Despite these differences, prior research has consistently shown elevated inflammatory cytokines, such as IFN-γ, IL-10, IL-6, IL-8, CXCL10, MIP-1α, MIP-1β, TNF-α, and IL-17 in MIS-C patients compared to healthy controls and other pediatric COVID-19 cases." (PMID 39931580, 2024). "Cytokines are messenger molecules of the immune system, including IL-6, IFN-α, IL-1β, IL-8, IL-10, IFN-γ, TNF-a, and C-reactive protein (CRP), and as such, they are closely related to the worst outcomes of COVID-19." (PMID 38012459, 2024). "Other components, such as interleukins (IL-2, IL-6, IL-7, IL-10) and TNF-α are connected to severe COVID-19 symptoms, where cytokine storm (a sudden increase in cytokines) occurs instead of a healthy immune response (Fricke-Galindo and Falfán-Valencia 2021)." (PMID 38240884, 2024). "Concentrations were significantly higher in the COVID-19+ cohort except for IL-1β, CXCL1, IL-10 and CXCL8." (PMID 38715114, 2024). "COVID-19 exhibited a distinct immunological profile characterized by increased levels of Th1 (IL-12 and IFN-γ) and Th2 (IL-4, IL-5, IL-10, and IL-13) cytokines, along with IL-1β and IL-6, among other markers." (PMID 39408907, 2024). "A comparative analysis of patients diagnosed with COVID-19, COVID-19 with concurrent maculopapular rash, or DRESS found that there were similar elevations of CXCL9, CXCL10, CXCL11, IFN-γ, IL-10, TNF-α, and IL-18 across the three groups." (PMID 39318634, 2024). "The aim of this study was to analyze the potential relationship between the level of selected cytokines (IL-6, IL-10, IL-12, IL-15, TNF-α) and inflammatory markers (CRP, NLR, PLR, LMR, SII) and the duration of rehabilitation in patients after COVID-19." (PMID 39335569, 2024). "Six cytokines and chemokines, IL-10, IP-10, HGF, SCGF-β, IL-16, and IL-18, were identified for analysing the progression patterns of COVID-19, especially IP-10, which was closely correlated with SOFA scores." (PMID 38710800, 2024). "Frequencies of TNF-α rs1800629 GA, AA, IL-8 rs4073 TA, AA, IL-10 (-1082 G>A), rs1800896 GA and GG, and CXCR2 rs2230054 CT genotypes were significantly higher in COVID-19 patients compared to the control group (p < 0.05)." (PMID 38544825, 2024). "IL-10 directly expands cytotoxic effector CD8+ T cells; hyper-activation of adaptive immunity in COVID-19 patients greatly exacerbates the disease condition." (PMID 38707035, 2024). "COVID-19 patients also revealed a major increase in C-reactive protein (CRP), IL-2, IL-4, IL-6, IL-10, TNF-α, and IFN-γ." (PMID 38540252, 2024). "There is a notable decrease in anti-inflammatory microorganisms, such as Faecalibacterium prausnitzii and Eubacterium rectale, in COVID-19 patients, which corresponds with elevated levels of tumor necrosis factor (TNF), interleukin-10 (IL-10), and CXCL10." (PMID 38779486, 2024). "In contrast, the Th2 cytokines IL-4 and IL-10 were moderately increased, suggesting the CD4 + T cell lineage is skewed towards Th2 in COVID-19." (PMID 38389037, 2024). "Elevated levels of IL-6, IL-10, and TNF-α have been shown to predict clinical progression to severe forms of COVID-19." (PMID 39203987, 2024). "Herein, we demonstrated the significant association between elevated levels of respiratory immune mediators (including IL-10, IL-6, MCP-1, and MCP-3) and COVID-19 severity." (PMID 39633683, 2024).
COVID-19 (continued). "A comparative analysis of cytokines in BALF and blood plasma of severe patients with ARDS against the background of COVID-19 showed increases in the levels of TNF-α, IL-1α, IL-1β, IL-1ra, IL-6, IL-10, and IL-33 cytokines relative to healthy donors." (PMID 39457048, 2024). "Higher levels of cytokines such as IL-6, IL-10, and TNF-α were observed in patients with severe COVID-19 compared to those with a mild and moderate course of COVID-19." (PMID 39063142, 2024). "In the longitudinal analysis of patients’ disease development, we found that the levels of five cytokines and chemokines, IL-10, IP-10, SCGF-β, IL-16, and IL-18, significantly changed during the progression from mild to severe and from severe to mild COVID-19." (PMID 38710800, 2024). "Longitudinal serum cytokine analysis of 207 COVID-19 patients revealed that in early inflammatory responses, IL-6, TNF-α, IL-10, and IL-1β expression increased in those with severe disease." (PMID 38710800, 2024). "In our previous study, we identified the potential of certain cytokines such as IL-10 and TNF-α to predict the severity and clinical outcome of COVID-19, using mathematical modeling." (PMID 38855114, 2024). "Compared with age-matched unexposed elderly individuals, convalescent COVID-19 patients presented with more IFN-γ and less IL-7, while IL-2, IL-6, IL-10, IL-12p70, IL-33 and CCL19/MIP-3 were unchanged." (PMID 38424104, 2024). "Interactions between the five genes shared by all the investigated metals and COVID-19 (CXCL8, IL1B, IL10, IL6, and TNF) are mainly physical, whereas the dominant interaction between the genes affected by individual metals is co-expression." (PMID 38963144, 2024). "Possible mechanisms explaining the association between DM and an increased risk for COVID-19 severity may be found in a higher Angiotensin-converting enzyme 2 (ACE2) expression in patients with DM, higher levels of TNFα, and lower levels of the anti-inflammatory cytokine, IL-10." (PMID 38610639, 2024). "In parallel, patients with severe COVID-19 showed reduced concentrations of key Th2-related mediators (MDC, IL-5) and likely compensatory production of the anti-inflammatory mediator IL-10." (PMID 38368384, 2024). "Eclitasertib also achieved numerically greater improvement in other inflammatory biomarkers including some of the markers of COVID-19 severity (leukocytes, neutrophil/lymphocyte ratio, LDH, IL-6, IL-8, and IL-6/IL-10) than placebo." (PMID 38419035, 2024). "IL-10, IL-6, MIP-1α, MCP-1, MCP-3, and TNF-α were significantly elevated in critical COVID-19 (OS7) compared to moderate COVID-19." (PMID 39494457, 2024). "It appears that the level of IL-10 is directly proportional to Gal-1, especially in stage III of COVID-19 and to CRP." (PMID 38540252, 2024). "Total ANA titers were less important than BMI, initial disease severity and age in the prediction of ongoing PASC at 21–24 weeks after COVID-19 onset, but more important than sex and early levels of CRP, IL6 and IL10." (PMID 39008486, 2024). "The levels of cytokines, including IL-6, IL-1β, IL-10, IFN-γ, tumor necrosisfactor-α (TNF-α), and colony-stimulating factor (CSF), gradually increase with theseverity of COVID-19 and play a crucial role in the immune response to SARS-CoV-2 infection." (PMID 39759510, 2024). "Nevertheless, we observed that circulating IL-6 and IL-10 values were associated with alterations of redox balance in patients with severe COVID-19, but not in typical ARDS, supporting the hypothesis that oxidative stress enhances the inflammatory response in the progression of SARS-CoV-2 infection." (PMID 37408073, 2023). "In the current study have been studied the relation between the levels of serum IL-10, TNF-α, INF-γ and TLR-4 and the presence of lymphopenia in COVID-19 patients group." (PMID 36864077, 2023). "We found that increased levels of Ang-II induced increased expression of the cytokines: IL-6, IL-10, IL-33, IL-28A and CD40L in the severe COVID-19 group." (PMID 38137381, 2023).